IL1B (interleukin 1 beta)
Diseases named in the same sentence as IL1B in open-access papers (continued):
Sharing a sentence is not in itself a finding about the gene and the disease.
Insulin resistance (continued). "While inflammasome assembly, caspase-1 activation, and IL-1β processing occur and promote insulin resistance in hepatocytes and mature adipocytes, secretion of IL-1β by these cells is controversial." (PMID 30116482, 2018). "Serum levels of insulin, Apelin, glucose, tumor necrosis factor-α(TNF-α), interleukin-1β (IL-1β) and the homeostasis model assessment of insulin resistance (HOMA-IR) were alsomeasured using commercial kits." (PMID 29845798, 2018). "Taken together, these results demonstrate that NLRP3 impaired the normal insulin signaling pathway and led to insulin resistance; IL-1β, a downstream molecular of NLRP3, also played a key role in regulating insulin sensitivity." (PMID 29096724, 2017). "Previous research showed IL-1β to be a key factor in the development of insulin resistance and suppression of insulin-induced glucose transport." (PMID 28661434, 2017). "Meanwhile, interleukin (IL)-1β and IL-6 production and secretion are induced by hypoxia in adipocytes, which are known to trigger systemic and local insulin resistance." (PMID 28353649, 2017). "Insulin resistance is a chronic inflammatory reaction, which involves the accumulation of various inflammatory factors, such as IL-1β." (PMID 28928791, 2017). "Our study showed that WMW inhibited IL-1β production and relieved insulin resistance in palmitate-treated HepG2 cells via reduction of the expression of the three components of NLRP3 inflammasome: NLRP3, ASC, and caspase-1 (p20)." (PMID 28928791, 2017). "We show that absence of REDD1 in macrophages decreases the expression of NLRP3, secretion of IL-1β and development of insulin resistance in adipocyte-macrophage coculture." (PMID 28765650, 2017). "Among the inflammatory cytokines, interleukin-1β (IL-1β) is believed to be mainly involved in insulin resistance, where it can activate nuclear factor kappa B (NF-κB) and promote the secretion of many other inflammatory factors." (PMID 28928791, 2017). "Recently, CPM and B1R were found upregulated along with the inducible nitric oxide synthase (iNOS) and interleukin-1β (IL-1β) in aorta, renal cortex and liver in a rat model of insulin resistance induced by high glucose feeding." (PMID 28824433, 2017). "Several inflammatory cytokines including TNF-a, IL-1b, and IL-6 have been identified as being involved in the development of insulin resistance." (PMID 27525022, 2016). "Our data establish that NLRP3 inflammasome-mediated increase of IL1β, TNFα and IL12-p40 in response to LPS-associated danger signals participate in the development of proinflammatory state, leading to insulin resistance." (PMID 27321128, 2016). "It was also found that ceramides induced the NLRP-3 inflammasome, driving the secretion of IL-1β followed by the development of insulin resistance." (PMID 26788518, 2016). "Insulin resistance also induces the expression of key inflammatory cytokine genes such as interleukin 1-beta in macrophages due to the interaction of NF-κB and FoxO1, a key transcription factor mediating insulin action." (PMID 27189661, 2016). "Neuropeptide Y (NPY) and interleukin 1 beta (IL1B) play important roles in insulin resistance and impairment." (PMID 27749914, 2016). "A hallmark of insulin resistance is the deposition of amyloid in the islets and this has been linked to the activation of NLRP3 inflammasome in local macrophages, triggering IL-1β processing and release." (PMID 26257839, 2015). "Activation of TLR-4 results in NF-κB activation and subsequent induction of vascular pro-inflammatory cytokines e.g. TNF-α and IL-1β that have also been demonstrated in inflammation after sub-acute and chronic stress and insulin resistance." (PMID 25826421, 2015). "Pro-inflammatory cytokines like IL-1β induces apoptosis in insulin-producing β-cells while CCL2 and TNFα are known to impair insulin signalling, and therefore causing insulin resistance." (PMID 27030821, 2015).
Insulin resistance (continued). "IL-1β induces peripheral insulin resistance, which contributes to the pathophysiology of GDM or pre-existing maternal obesity." (PMID 25849717, 2015). "Leptin, an adipocytokine involved in the pathogenesis of insulin resistance necessary for developing type 2 diabetes, induces β-cell apoptosis and impaired β-cell function by promoting IL-1β production in human pancreatic islets." (PMID 25403235, 2014). "Despite the importance of IL-1β as a macrophage-derived mediator in inducing insulin resistance in human adipocytes, the contribution of other factors produced by macrophages cannot be overlooked." (PMID 24918199, 2014). "In conclusion, our study demonstrates that IL-1β is a key factor in mediating macrophage-induced insulin resistance in human adipocytes." (PMID 24918199, 2014). "IL-1β, a proinflammatory cytokine, is suggested to be involved in the development of insulin resistance." (PMID 24918199, 2014). "Further, NLRP3 upregulates the pool of proinflammatory cytokines such as IL-1β, IL-18, and IFNγ and promotes insulin resistance in M1 macrophages." (PMID 24744784, 2014). "Recent studies suggest IL-1β as a putative candidate in the development of insulin resistance and type 2 diabetes." (PMID 24918199, 2014). "Disproportionate lipid accretion from excess caloric intake promotes infiltration of innate immune cells followed by increased secretion of cytokines such as IL‐1β and TNFα which instigate a chronic inflammatory response resulting in insulin resistance." (PMID 25096554, 2014). "Yet, in the fat explant/primary-hepatocyte system, antagonizing IL-1β with IL-1Ra only partially, and with marginal statistical significance, prevented the insulin resistance observed in liver cells." (PMID 23341960, 2013). "Ex-vivo, adipose explants co-cultured with primary hepatocytes from WT or IL-1-receptor (IL-1RI)-KO mice suggested only a minor direct effect of adipose-derived IL-1β on hepatocyte insulin resistance." (PMID 23341960, 2013). "The resulting activation of caspase-1 and subsequent secretion of IL-1β then interfere with insulin signaling, whereas inhibition of caspase-1 has been demonstrated to attenuate insulin resistance coincident with improved function of adipocytes." (PMID 23964268, 2013). "The relative expression value of IL-1β in HF group was 1.75 times higher than that in NC group, indicating obvious inflammation occurred in islets of insulin resistance rats." (PMID 23197974, 2012). "In this study, the increased content of IL-1β was also found in islets of insulin resistance rats, which was increased more after STZ treatment, indicating an obvious inflammation damage intra islets." (PMID 23197974, 2012). "We found clear evidence that signals for IL-1β, IL1RN, TNF-α and TGFβ-1 are present in both adipose and liver tissues and that these are linked to the development of inflammation and insulin resistance in the HFC-fed mice." (PMID 21410952, 2011). "Only a few studies have examined the role of IL-1α as a mediator for cellular insulin resistance in sharp contrast to a number of reports on IL-1β." (PMID 22216303, 2011). "NF-κB causes insulin resistance by stimulating proinflammatory cytokines like TNF-α, IL-6, IL-1β, and resistin, which in turn activates JNK and NF-κB pathways to create a vicious cycle that will exacerbate tissue damage." (PMID 20508722, 2010). "Paradoxically, chronic IL-1β exposure leads to sustained NF-κB activation, which subsequently suppresses PPARγ and C/EBPα expression, ultimately inhibiting adipogenesis and inducing insulin resistance." (PMID 41508030, 2026). "The pro-inflammatory cytokine environment in IBD, involving molecules like TNF-α, IL-6, and IL-1β, appears to exacerbate insulin resistance, especially in older individuals who may already be more vulnerable to metabolic disturbances." (PMID 41007787, 2025).
Insulin resistance (continued). "CAPS2 may influence insulin resistance and beta cell dysfunction by regulating the release of inflammasomes and pro-inflammatory cytokines, such as IL-1β." (PMID 40296871, 2025). "HCV also induces IL-1β and IL-6, which are well known for inducing insulin resistance." (PMID 41012578, 2025). "Furthermore, UA can activate the NLRP3 inflammasome, subsequently inducing the secretion of pro-inflammatory cytokines including Interleukin-1β (IL-1β), which exacerbates hepatic inflammation and insulin resistance (IR)." (PMID 41341141, 2025). "Moreover, exercise-induced secretion of interleukin-6 (IL-6) from muscle cells has anti-inflammatory effects by inhibiting cytokines like tumor necrosis factor alpha (TNF-α) and interleukin-1 beta (IL-1β), contributing to reduced insulin resistance." (PMID 41008394, 2025). "However, in future studies, these findings must be observed and interpreted in parallel to changes in IL-1β, a cytokine increasingly recognized as a central player in the development of insulin resistance and type 2 diabetes and that is antagonized by IL-1ra." (PMID 40145019, 2025). "Additionally, TXNIP is a key activator of the NLRP3 inflammasome, a complex that triggers the maturation and release of pro-inflammatory cytokines like IL-1β, which directly promote insulin resistance and β-cell damage." (PMID 41300521, 2025). "By targeting IRS-1, IL-1β is capable of impairing insulin signaling and action and could thus participate (in combination with other cytokines) in the development of insulin resistance in adipocytes." (PMID 41012578, 2025). "In this context, our results indicate that tirzepatide may restore insulin signaling and mitigate insulin resistance, at least in part, through the suppression of Il1b expression." (PMID 41019552, 2025). "Furthermore, lower TXNIP levels directly inhibit the sparking of the NLRP3 inflammasome, an essential sensor that stimulates the production of pro-inflammatory cytokines like IL-1β that are connected to insulin resistance and β-cell mortality." (PMID 41300521, 2025). "The immune system’s pro-inflammatory environment in IBD, characterized by cytokine dysregulation (e.g., TNF-α, IL-6, IL-1β), may contribute to systemic inflammation, further exacerbating insulin resistance in older individuals." (PMID 41007787, 2025). "Moreover, IL-1β has been shown to promote insulin resistance in vitro, both in mouse adipocytes and hepatocytes." (PMID 39433211, 2025). "The anti-cytokine immunotherapy of type 2 diabetes is a new treatment method in recent years, especially blocking IL-1β in the process of impaired insulin secretion and insulin resistance, and can be used as a potential therapeutic target to reverse the quality and function of β cells." (PMID 40066372, 2025). "Unlike IL-6 or IL-1β, which are strongly linked to inflammation and insulin resistance in T2D, IL-7 has not been clearly associated with metabolic inflammation or glucose metabolism." (PMID 40804870, 2025). "Furthermore, IL6, IL1B, and TNF are pro-inflammatory cytokines, which are associated with insulin resistance and the development of chronic inflammation." (PMID 40699728, 2025). "Mechanistically, it promotes inflammation via IL-6, TNF-α, and IL-1β and may contribute to insulin resistance." (PMID 41464844, 2025). "The distinct adipogenic and inflammatory effects of IL-1β on hASCs depending on treatment timing and duration may explain why some previous studies described an anti-adipogenic (and insulin resistance-inducing) effect of IL-1β35,80,81." (PMID 39261467, 2024). "Chronic inflammation resulting from GD-induced increases in the levels of inflammatory factors, such as IFN-γ, IL-1β, and TNF-α in vivo, may contribute to insulin resistance and increase the risk of developing T2D by affecting insulin sensitivity." (PMID 39568808, 2024).
Insulin resistance (continued). "Interestingly, six of the cytokines elevated in 3n mice that were attenuated with the Ch+ diet (IL-1α, IL-1β, IFN-γ, TNF-α, IL-3, and IL-6) have been associated with the development of insulin resistance in T2D." (PMID 39683562, 2024). "IL-1β has recently become the most prominent cytokine attributed to inducing insulin resistance." (PMID 39606781, 2024). "Furthermore, at least some cytokines (e.g., IL-1β) can promote insulin resistance in isolated human adipocytes." (PMID 39225103, 2024). "Additionally, adipocytes have the capability to release pro-inflammatory cytokines like TNF-α and IL-1β, which are factors contributing to the development of insulin resistance." (PMID 39606781, 2024). "However, after weight loss in obese T2DM patients, the expressions of IL-1β and NLRP3 inflammasome are decreased, and the FBG and insulin resistance in T2DM patients are also decreased." (PMID 38725443, 2024). "Additionally, elevated levels of IL-1β have been proved to promote insulin resistance and liver inflammation, whereas IL-10 has the opposite effect." (PMID 38302976, 2024). "In terms of insulin resistance, IL-1β interferes with insulin signaling by activating stress kinases like JNK and inhibitor of nuclear factor kappa B kinase subunit beta (IKKβ), which phosphorylate insulin receptor substrate proteins and disrupt downstream insulin signaling cascades." (PMID 38044678, 2024). "IL-1β and IL-18 also contribute to adipose tissue inflammation and insulin resistance, and the significant reduction in their mRNA levels following CGWE treatment indicates its potential to mitigate these inflammatory pathways and improve metabolic health in obese individuals." (PMID 37571229, 2023). "It inhibits caspase-1 and the formation of IL-1β and as such it also lowers insulin resistance." (PMID 37762961, 2023). "Additionally, both IL-17 and IL-1β can promote insulin resistance in adipocytes and favor the development of DM2 in obese individuals." (PMID 36788619, 2023). "However, as insulin resistance persists, the prolonged action of IL-1β stimulates the generation of a wide array of cytokines and chemokines such as IL-6, IL-8 and IL-33." (PMID 37032781, 2023). "Indeed, several studies have reported increased levels of TNF-α, IL1-β, and IL-6 in adipose tissue that can lead to insulin resistance." (PMID 37892881, 2023). "Screening identifies TNFα and IL1β as the mediators of insulin resistance in iPSC-Heps." (PMID 37400454, 2023). "CR could prevent the production of mature IL-1β and inhibit insulin resistance as a consequence of a high-fat diet in a mouse model." (PMID 37009013, 2023). "Besides, mitochondrial damage produces a large amount of ROS, which induces the release of inflammatory factors [such as TNF-α, interleukin 1β (IL-1β) and IL-6] and disrupts pancreatic β-cell function, further aggravating insulin resistance." (PMID 37828472, 2023). "Furthermore, IL‐1β can promote the release of inflammatory cytokines by mediating pancreatic β‐cell apoptosis or activating the NF‐κB pathway, thereby inducing insulin resistance and the development of type 2 diabetes." (PMID 37181308, 2023). "Moreover, IL-1β promotes the release of inflammatory cytokines by mediating islet β-cell apoptosis or activating the NF-κB pathway, thereby inducing insulin resistance and type 2 diabetes." (PMID 37693249, 2023). "TNF-α, IL-1β, and IL-6 released by adipose tissue resident macrophages could lead to insulin resistance." (PMID 37693353, 2023). "Significant correlations were also found between IL-1β and insulin resistance." (PMID 35303833, 2022). "Of note, immune cells from SVF could also be involved in controlling IL-1β release and promoting HF diet-mediated insulin resistance." (PMID 36234919, 2022).
Insulin resistance (continued). "Transgenic mice lacking NLRP3 fed with a high-fat diet, which has previously been shown to activate NLRP3, have lower IL-1β and are protected from high-fat diet-induced insulin resistance, further supporting inflammatory mediators’ involvement in metabolic inflammation and insulin resistance." (PMID 35754962, 2022). "Kupffer cells incubated with bovine serum albumin (BSA)-palmitate for 24 h expressed higher levels of the pro-inflammatory cytokines IL-6, TNFα and IL-1β, all of which are known to induce insulin resistance, than Kupffer cells incubated with BSA-oleate or BSA-control." (PMID 35955975, 2022). "Moreover, IL-1β was related with insulin resistance, and IL-10 inversely correlated with neonatal BW." (PMID 35303833, 2022). "However, PBEH improved insulin resistance and reduced the lipid peroxide and IL-1β contents in the hippocampus better than donepezil." (PMID 35328781, 2022). "IL-1β and IL-6 have been shown to induce insulin resistance in adipocytes." (PMID 35625866, 2022). "Furthermore, the treatment of T2DM mice with MEP resulted in reduced endotoxemia and insulin resistance-related pro-inflammatory cytokines interleukin 1β (IL-1β), tumor necrosis factor-alpha (TNF-α), and interleukin 6 (IL-6)." (PMID 36276816, 2022). "Several studies have shown that acupuncture can improve insulin resistance by reducing serum IL-6, IL-8, and IL-1β levels, which might help protect islet B cell function." (PMID 37675019, 2022). "With the induction of lipopolysaccharide and saturated fatty acid, M1 macrophages can activate and secrete tumor necrosis factor α (TNF-α), interleukin-6 (IL-6), interleukin-12 (IL-12), interleukin-1β (IL-1β) and other pro-inflammatory factors, leading to inflammation and insulin resistance." (PMID 35757707, 2022). "Interestingly, high blood levels of pro-inflammatory cytokines IL-6, IL-1B, and high sensitivity C-reactive protein (hsCRP), a clinical marker of inflammation, in obese patients are predictors of insulin resistance and hyperglycemia." (PMID 36247456, 2022). "Elevated concentrations of TNF-α, IL-1b, IL-6 and leptin may also worsen insulin resistance and increase fetal overgrowth." (PMID 35957820, 2022). "With the discovery that NLRP3 inflammasome mediates caspase-1 activation and IL-1β maturation, its relation with insulin resistance and type 2 diabetes development has been recognized; NLRP3 deficiency protects mice from obesity-induced insulin resistance." (PMID 36741414, 2022). "IL-1β participates in insulin resistance through NF-κB pathway." (PMID 36230963, 2022). "Additionally, IL-1β depletion completely changes the inhibitory effect of MC medium on insulin signaling molecules like IRS-1 and PI3K, which indicates that IL-1β is a key factor in mediating macrophage-induced insulin resistance in adipocytes." (PMID 36230963, 2022). "In addition, anti-inflammatory drugs targeting TNF-α, IL-1β, and NF-kB improved insulin resistance and fasting blood glucose levels in clinical studies." (PMID 36145139, 2022). "Under a hyperglycemic environment, ROS activates the NLRP3 inflammasome in β cells, elevating caspase-1-dependent IL-1β secretion; this mediates dysfunction of β-cell insulin secretion and promotes obesity and insulin resistance, finally leading to pyroptosis and the development of T2DM." (PMID 35355717, 2022). "In support of such a hypothesis, insulin increased the formation of IL-1β in U937 macrophages and thereby impaired the insulin-dependent induction of glucokinase in a cell-based model of hepatic insulin resistance." (PMID 35955975, 2022). "Insulin resistance is associated with an increase of TNF-α, IL-1α, IL-1β, IL-6, and leptin." (PMID 34970568, 2021).